PDGFRB (platelet derived growth factor receptor beta)
Diseases named in the same sentence as PDGFRB in open-access papers (continued):
Sharing a sentence is not in itself a finding about the gene and the disease.
lymphoid neoplasm (29 papers, 2009 to 2025). A neoplasm composed of a lymphocytic cell population which is usually malignant (clonal) by molecular genetic and/or immunophenotypic analysis. "While these reports revealed it is not uncommon for PDGFRA and FGFR1 genetically rearranged cells to differentiate into lymphoid neoplasms, hematologic diseases bearing PDGFRB mutations are rare." (PMID 22356850, 2012). "Platelet-derived growth factor receptor beta (PDGFRB)-rearranged myeloid/lymphoid neoplasms (MLNs) are rare hematologic malignancies typically responsive to tyrosine kinase inhibitors (TKIs) such as imatinib." (PMID 41278291, 2025). "Primary eosinophilic disorders are rare in the pediatric population and include chronic eosinophilic leukemia; myeloid/lymphoid neoplasms with rearrangements of PDGFRA, PDGFRB, FGFR1, or PCM1-JAK2; and idiopathic hypereosinophilic syndrome." (PMID 41552084, 2025). "Mastocytoses were also listed within the spectrum of MPNs, while myeloid/lymphoid neoplasms with PDGFRA, PDGFRB, and FGFR1 rearrangements were considered separately." (PMID 34830822, 2021). "The current 2017 WHO classification recognizes the following specific diseases: M/LNs-Eo with rearrangements of PDGFRA, PDGFRB and FGFR1 respectively and the provisional entity of myeloid/lymphoid neoplasms with PCM1-JAK2 rearrangement." (PMID 34205834, 2021). "The database showed that both PDGFB and PDGFRB were highly expressed in Cholangiocarcinoma (CHOL), Liver hepatocellular carcinoma (LIHC), Lymphoid Neoplasm Diffuse Large B-cell Lymphoma (DLBC), Pancreatic adenocarcinoma (PAAD and Head and Neck squamous cell carcinoma (HNSC)." (PMID 37307823, 2024). "Therefore, this disease belongs to the new WHO category of myeloid and lymphoid neoplasms with abnormalities in PDGFRA, PDGFRB and FGFR1 genes." (PMID 22356850, 2012).
Stroke (29 papers, 2015 to 2025). Sudden impairment of blood flow to a part of the brain due to occlusion or rupture of an artery to the brain. "In comparison, PDGFRβ-expressing stromal cells increase in density but remain mostly associated with the vasculature in stroke patients with subcortical ischemic lesions and in the stroma of aggressive grade IV human GBM tumors." (PMID 34535655, 2021). "In logistic regression models adjusted for age, sex, vascular risk factors, and stroke subtype, PDGFRβ and Endo‐1 were associated with decreased odds of lacunes (OR per 1 SD increase in PDGFRβ = 0.71, 95% CI:0.50, 0.99; OR per 1 SD increase in Endo‐1 = 0.71, 95% CI:0.49, 0.99)." (PMID 40275856, 2025). "The number of CD31+ ECs and PDGFRβ+ pericytes decreased in immunofluorescence at RP34D after stroke when E-pericytes were depleted by DTA, indicating decreased microvasculature." (PMID 40667795, 2025). "By day 5, ITGA8‐expressing cells become more prominent, coinciding with more PDGFRβ+ cells on vessels, signaling the start of post‐stroke angiogenesis." (PMID 41085070, 2025). "Our group has recently demonstrated that PDGF‐D, which specifically binds to PDGFRβ, plays a major role in stabilizing the angiogenic vasculature after stroke by rescuing the functions of pericytes and crosstalk with brain endothelial cells." (PMID 40277075, 2025). "After stroke, the increased expression of PDGFRβ is vital for the restoration of the microvasculature and BBB function, as well as for neuro-reparative cascades within the ischemic core region." (PMID 36508132, 2023). "It is of note that the expression of vascular markers (CD31 and PDGFRβ) remains stable with stroke stage within the same region (online resource)." (PMID 35752654, 2022). "Other studies have also indicated that increased PDGFRβ expression in pericytes is a marker for their activation in stroke and traumatic brain injury." (PMID 35301433, 2022). "The number of recombined PDGFRβ+ stromal cells that had drastically increased in the ischemic lesion core at 5 days after stroke declined over time along with condensation of the lesion, keeping the cell density stable." (PMID 34535655, 2021). "At both 5 days and 14 days after stroke, we found an increased number and density of recombined PDGFRβ+ stromal cells compared to the contralateral stroke side." (PMID 34535655, 2021). "At all time points investigated, we observed an increase in the number of lineage traced type A pericytes co-expressing EYFP and PDGFRβ, compared to the contralateral stroke side." (PMID 34535655, 2021). "In support of this idea, previous studies showed that brain endothelial-cell-derived trophic factors, such as PDGFB and basic fibroblast growth factor, promote the induction of PDGFRβ+ pericytes within ischemic areas after stroke." (PMID 32887241, 2020). "Immunohistochemistry at 1 d post stroke showed PDGFRβ+ pericytes within the ischemic areas after 90-min t-MCAO (E’) and p-MCAO (F’)." (PMID 32492968, 2020). "The number of Iba1 and PDGFRβ double-positive cells and the populations of Iba1+ cells relative to PDGFRβ+ cells were analyzed at post-stroke days 3, 5, and 7 within the ischemic core and peri-ischemic areas." (PMID 26952098, 2016). "Immunohistochemistry at post-stroke day 3 showed that some PDGFRβ+ cells co-express the microglial marker CD206." (PMID 26952098, 2016). "Our analysis demonstrated that PDGF-D increased the coverage of CD31+ microvessels by PDGFRβ+ pericytes (P = 0.0568), and reduced the ratio of pericytes that are not attached to endothelial cells at the lesion site, 1 week after stroke." (PMID 38769116, 2024). "In addition to neural regeneration, early reperfusion promoted PDGFRβ+ pericyte proliferation at acute period (7 d post stroke)." (PMID 32492968, 2020). "On post-stroke day 3, only a small portion of PDGFRβ+ cells expressed Iba1." (PMID 26952098, 2016). "However, this number began to increase on post-stroke day 5, suggesting that PDGFRβ+ iPCs could generate microglia." (PMID 26952098, 2016).
Stroke (continued). "The accumulation of pericytes and upregulation of PDGFRβ and PDGFβ expression in the infarct area after stroke can be observed, suggesting that these cells promote angiogenesis and BBB repair after stroke." (PMID 40371544, 2025). "Post‐stroke, days 1 and 3 see a sharp drop in ITGA8‐expressing cells on vessel walls, similar to PDGFRβ+ cells." (PMID 41085070, 2025). "Expression of IGF1, which has been reported to provide protection after stroke by improving CBF and BBB function, is induced in reactive PDGFRβ+ pericytes upon increasing PDGF-D brain abundance." (PMID 38769116, 2024). "VEGF‐E increased the overall density of perivascular PDGFRβ+ cells at the injury site 4 days after stroke without compromising the coverage of PDGFRβ+ cells for CD31+ microvessels." (PMID 40277075, 2025). "Additionally, we isolated PDGFRβ+ brain cells from ITGA8‐Cre; H11‐GFP‐tdTomato mice on day 5 post‐stroke using fluorescence‐activated cell sorting and observed similar changing patterns of ITGA8+ cells compare to sham‐operated mice." (PMID 41085070, 2025). "For example, in a study comparing PDGF receptor β (PDGFRβ) serum levels in patient groups with a history of stroke or ischemic attack versus without, patients with CVD events had significantly increased levels of PDGFRβ, indicative of BBB injury." (PMID 39766777, 2024). "Transcription factor CoupTF2 (nuclear) was expressed by the Col1a1+ meninges (carets) and by Col1a1+ PSCs at P0 (arrows), P21 (arrows) and in the stroke lesion by PDGFrβ+ PSCs (arrows) but not by Ib4+ macrophages (carets)." (PMID 27422020, 2016). "Moreover, the EGFP+ CD31- cells expressed classic pericyte markers (CD13, PDGFRβ, and NG2), which also indicated ECs might turn into pericyte-like cells after stroke." (PMID 40667795, 2025). "Thus, we next investigated PDGFRβ+ and ERG+ cell expression patterns 7 d post stroke." (PMID 32492968, 2020).
colon carcinoma (27 papers, 2010 to 2025). "Different studies have indicated that PDGF and PDGFRβ are expressed by tumor cells as well as tumor-associated endothelial cells, pericytes, and other stromal cells in colon carcinomas, which are thought to provide a favorable microenvironment for the growth and survival of cancer cells." (PMID 23900414, 2013). "Furthermore, PDGFRβ expression levels are associated with angiogenesis, invasion and metastasis of colon cancer." (PMID 23900414, 2013). "Our analysis of primary human colon tumor samples demonstrated upregulation of the PDGFRβ, VEGFR1, and VEGFR2 genes in UICC stage I-III tumors." (PMID 36264073, 2022). "We found increased levels of THBS4 and PDGFRb in tumor tissues compared to normal tissues of colon cancer patients." (PMID 32899998, 2020). "In ImPACCT, patients with CMS4 colon cancer are identified with a recently developed 4-gene RT-qPCR test that measures PDGFRA, PDGFRB, PDGFC and KIT expression levels in diagnostic tumour biopsies." (PMID 28424071, 2017). "The data revealed a variable expression of these receptors in different tumors, with fibroblast expression of PDGFRβ most common in lung and colon tumors." (PMID 27128408, 2016). "In colon cancer cells and tumors previously exposed to curcumin combined with sildenafil we discovered that the cells had evolved to express higher levels of PDGFβ concomitant with elevated PDGFRβ phosphorylation in the tumor cells." (PMID 32983965, 2020). "Consistent with the PDX analysis, we found enhanced staining for CD31, CD105, CD34 (mature and immature blood vessel marker) and PDGFRB in colon tumors from p38αΔUb mice, suggesting that p38α downregulation stimulated tumor vessel density and perivascular cell recruitment." (PMID 31296856, 2019). "By contrast, in colon carcinoma cell lines expression of PDGFRβ at the mRNA level was lower." (PMID 23900414, 2013). "Accordingly, PDGFRβ-directed treatments, such as STI571 or DNA vaccines, have led to apoptosis of tumor-associated pericytes and endothelial cells and thus to confine the vasculature to an immature stage in colon tumors." (PMID 22205974, 2011). "Given the observed overexpression of PDGF/VEGF receptors in human colon cancer tumors, we analyzed several CRC cell lines for the expression of PDGFRα, PDGFRβ, VEGFR1, and VEGFR2." (PMID 36264073, 2022). "We demonstrated that the gene expression of PDGFRβ, VEGFR1, and VEGFR2 was significantly higher in our cohort of UICC stage I-IV colon cancer patients compared to normal colon mucosa." (PMID 36264073, 2022). "To follow up on our previous finding of PDGF overexpression in CRC, we analyzed the expression of its corresponding receptors, PDGFRα and PDGFRβ, and presumed cross-binding partners, VEGFR1 and VEGFR2, in primary human colon cancer tissue samples (n = 42)." (PMID 36264073, 2022). "As shown, in both HT-29 cells and primary human colon cancer cells (“pri-Can-1”), NINJ2 co-immunoprecipitated with EGFR, PDGFRα, PDGFRβ and FGFR." (PMID 31597121, 2019). "Notably, PDGF-D leads to phosphorylation of PDGFRβ, promotes CRC cell migration, invasion, and proliferation, and is highly expressed in human colon cancer DLD-1 cells." (PMID 32899998, 2020). "Therefore, to investigate the effects of TGFβ on PDGFRβ and THBS4 overexpression in CRC, we examined the mRNA levels of PDGFRβ and THBS4 after treatment with TGFβ for 12 h in DLD-1 cells, which is a colon cancer cell line." (PMID 32899998, 2020). "Given that the anti-CCL5 strategy could only lead to a moderate therapeutic effect against colon cancer, we next sought to evaluate the potential of CCL5 blockade administered in combination with an anti-PDGFRβ strategy." (PMID 22205974, 2011). "Immunohistochemistry analysis using PDGFRB (CD140b) as a perivascular cell marker, and CD31 or CD105 as markers for mature or immature blood vessels, respectively, showed an enhanced number of blood vessels and perivascular cells in the colon tumors upon p38α inhibition." (PMID 31296856, 2019).
colon carcinoma (continued). "Interestingly, double staining experiments revealed the co-expression of CD31 with PDGFRB or CD146 (M-CAM) in blood vessels of colon tumors from p38αΔUb but not WT mice." (PMID 31296856, 2019). "Immunohistochemical studies on human colon cancer specimens revealed inter- and intratumoral heterogeneity for the expression of different receptor tyrosine kinases (RTKs), including EGFR, vascular endothelial growth factor receptor-2 (VEGFR2), and platelet-derived growth factor receptor β (PDGFRβ)." (PMID 23900414, 2013).
myeloid neoplasm (24 papers, 2012 to 2024). Proliferation of myeloid cells originating from a primitive stem cell. "For myeloid tumor patients with PDGFRB fusion gene, imatinib was associated with long lasting and long-term remission." (PMID 33663081, 2021). "Here, we characterized a series of 14 cases with a myeloid neoplasm at diagnosis and a rearrangement of PDGFRB, providing data from in-depth genomic characterization by SNPa and NGS analysis." (PMID 34859285, 2022). "Patients with myeloid neoplasms with PDGFRB rearrangement have been treated with imatinib at a dose of 100–400 mg/day." (PMID 30697976, 2019). "Translocation with 12p13 (ETV6; MIM #600618) is reported to be present in 69% of patients with PDGFRB‐rearranged myeloid neoplasms." (PMID 30697976, 2019). "Soon after admission, with the presumptive diagnosis of myeloid neoplasm with PDGFRB rearrangement, the patient was started on imatinib 200 mg/day." (PMID 27746819, 2016). "Cases that have either a PDGFRA or PDGFRB mutation associated with mast cell hyperplasia should be properly classified as “myeloid neoplasms with PDGFRA or PDGFRB rearrangements,” according to the World Health Organization’s classification system." (PMID 24141298, 2013). "Several genetic abnormalities such as PDGFRα, PDGFRβ or FGFR1 have been observed in PDGFR-rearranged myeloid neoplasm, and the FIP1L1-PDGFRα fusion gene generated by the interstitial deletion on chromosome 4q12 has been reported to account for 5% to 15%." (PMID 24009732, 2013). "CSF1R codes for a cytokine that controls the monocyte-macrophage system and PDGFRB is involved in various myeloid malignancies." (PMID 22253721, 2012). "Therefore, the patient was diagnosed as systemic mastocytosis-related myeloid tumor with basophilia and PDGFRB abnormalities." (PMID 33663081, 2021). "Various translocations involving the PDGFRB gene are identified in myeloid neoplasms." (PMID 27648315, 2016). "It is worth noting that a diagnosis of MPN-U cannot be made in cases with genetic lesions defining other myeloid neoplasms (BCR-ABL1 fusion, rearrangements of PDGFRA, PDGFRB, FGFR1 and/or PCM1-JAK2 fusion), if clinical data are incomplete or if biopsy samples are inadequate." (PMID 34830822, 2021). "We present the case of a 26-year-old woman with microcytic anemia, basophilia, thrombocytosis, and massive splenomegaly, who was found to have systemic mastocytosis and associated clonal hematological non-mast cell lineage disease (SM-AHNMD), with myeloid neoplasm with PRKG2/PDGFRB rearrangement." (PMID 27648315, 2016).
neuroblastoma (24 papers, 2008 to 2025). Neuroblastoma (NB) is the most common solid, extracranial childhood tumor. "NSC309874, which did not significantly interact with the PDGFRβ G4 structures, repressed PDGFRβ transcription in an aggressive neuroblastoma cell line indicating the potential of this compound as a new PDGFRβ inhibitor." (PMID 33513764, 2021). "Similar to the in vitro studies AS STRAP KO tumors exhibited decreased protein expression of PDGFRβ, which is known to promote tumor growth in neuroblastoma." (PMID 34206917, 2021). "Regorafenib treatment also inhibited 13-cis-retinoic acid-induced RET phosphorylation, and led to reduced expression of FGFR1 and PDGFRβ, with incomplete inhibition of FGFR1 and PDGFRβ phosphorylation also noted in tested neuroblastoma cell lines." (PMID 32457362, 2020). "Flow cytometric analysis confirmed differences in the expression of MAP2, β-catenin, and PDGFRβ while all neuroblastoma cells were nestin positive." (PMID 22891161, 2012). "Interestingly, cisplatin has been described to reduce PDGFRB expression in neuroblastoma cells." (PMID 28192521, 2017). "In contrast, Dp44mT and DpC consistently downregulated PDGFRβ and IGF-1R in both neuroblastoma cell lines." (PMID 36160437, 2022). "We previously reported on the PDGFRB-induced transactivation of EGFR in medulloblastoma and neuroblastoma cells that was effectively abrogated with imatinib and sunitinib." (PMID 34422720, 2021). "Tumoral pericytes isolated from childhood ependymoma and neuroblastoma specimens displayed angiogenic properties in vitro and expressed typical markers, including CD146, NG2, and PDGFRβ." (PMID 28553358, 2017). "Specifically, we treated SH-SY5Y neuroblastoma cells with the BB homodimer of PDGF (PDGF-BB), which resulted in PDGFRβ phosphorylation and subsequent ERK activation." (PMID 18312689, 2008). "We therefor believe that sutent may play anti-self-renewal and anti-malignancy roles in neuroblastoma tumorspheres by inhibiting the protein expression of the stemness-maintenance drivers, SOX2 and PDGFRβ as well as the malignant, proliferative markers MYCN and survivin." (PMID 29298329, 2018).
meningioma (22 papers, 2013 to 2025). A generally slow growing tumor attached to the dura mater. "One NF2 wild type meningioma (28M) had PDGFRB and RAD50 mutations." (PMID 35049691, 2022). "Meningiomas are also highly vascular tumors and most meningiomas express PDGFRβ." (PMID 40076810, 2025). "Additionally, epidermal growth factor receptors (EGFRs) tend be overexpressed in grade I meningiomas, and the platelet-derived growth factor receptor beta (PDGFRB) gene is upregulated and overexpressed in this type of tumour." (PMID 31865413, 2020). "Indeed, increasing tumor grade is associated with increased expression of VEGF, Ki67, TOP2, PD-1, and PDGFRB, while hypermethylation of RIZ1 and WNK2 leads to loss of protein expression in high grade meningioma." (PMID 31970090, 2019). "PDGFRB and its ligand PDGFBB are also overexpressed in meningioma, with higher levels observed in high grade atypical tumors as compared to benign." (PMID 31970090, 2019). "Different growth factor receptors and kinases may promote the meningioma growth, including epidermal growth factor receptor (EGFR), platelet-derived growth factor receptor β (PDGFRβ), vascular endothelial growth factor receptor (VEGFR), and insulin-like growth factor receptor (IGFR)." (PMID 35565385, 2022). "Additionally, there were eight kinases that were not significantly differently expressed between meningioma and VS present in the macrophages (LCK, PDGFRB, FGFR1, FLT1, CSK, MEK, MAP2K2, and ERBB2)." (PMID 41437121, 2025).
non-small cell lung carcinoma (22 papers, 2011 to 2026). A group of at least three distinct histological types of lung cancer, including non-small cell squamous cell carcinoma, adenocarcinoma, and large cell carcinoma. "Further in vivo assays such as non-small cell lung cancer patient-derived xenograft models which express high level of PDGFRβ, VEGFR2, EGFR, C-Kit will be carried out to demonstrate that whether R8 can be developed into a new member of MKI drug family." (PMID 29152075, 2017). "In non-small cell lung cancer (NSCLC), several studies have explored the prognostic significance of established CAF markers such as podoplanin, vimentin, FAP-1, αSMA or PDGFRβ." (PMID 29415055, 2018).